HIF1A (hypoxia inducible factor 1 subunit alpha)
Diseases named in the same sentence as HIF1A in open-access papers (continued):
Sharing a sentence is not in itself a finding about the gene and the disease.
tumor (continued). "Another interesting protein with high expression at the TM is the N-myc downstream-regulated gene 1 (NDRG1 pT346) which is regulated by HIF-1α, stress and growth signals, and may be a marker of tumor progression." (PMID 29142297, 2017). "From the erlotinib study, we can speculate that Compound 12 might enhance the effects of gefitinib not only by inhibiting HIF-1α synthesis, but also by inducing vascular normalization, resulting in improved vascular delivery of gefitinib to the tumor tissues." (PMID 27999195, 2017). "SIRT3 acts as a tumor suppressor by inhibiting ROS production and activation of HIF1α." (PMID 28423723, 2017). "Endostatin can inhibit RT-induced increases in the expression of the angiogenic factors HIF-1α and VEGF, effects that may underlie its enhancements of tumor radiosensitivity." (PMID 29282026, 2017). "Thus, since HBOT enhanced the pO2 in tissues temporarily, and O2 is important for degrading HIF-1a, we expected reduction in tumor growth." (PMID 28832662, 2017). "Even though hypoxia represents the primary stimulus driving HIF-1α accumulation, HIF-1α was also observed in oxygenated tumor areas and metastatic nodules, suggesting that other mechanisms (in addition to O2 deficiency) regulate HIF-1α stabilization and HIF-1 activation." (PMID 29100428, 2017). "Since VEGF-A is secreted by tumor cells through the activation of HIF-1α we reasoned that STK33 might affect VEGF levels." (PMID 29100402, 2017). "Hypoxia-induced overexpression of HIF-1α in MPNST cells might affect the proliferative phenotype of tumor cells; thus, we next compared the proliferation of normal and MPNST cell lines under hypoxic and low-serum culture conditions." (PMID 28558056, 2017). "Furthermore, AGT-silencing similarly resulted in reduced expression of HIF-1α protein in hypoxic tumor cells." (PMID 28205588, 2017). "It seems that the AMPK control of HIF-1α may be dependent on the contexts and phases of tumor progression, concordantly to the recently reviewed double-edged role of this energy sensor." (PMID 29230384, 2017). "Due to the critical role of BCL9 in promoting tumor development in the Wnt/β-catenin signaling pathway, the specific regulation of BCL9 expression by HIF1α is considered to be an underlying crosstalk between Wnt/β-catenin signaling and hypoxia signaling pathways." (PMID 28074862, 2017). "Besides, hypoxia is a common phenomenon at sites of inflammatory lesions and acts as a microenvironmental factor to enhance tumor angiogenesis by inducing HIF-1α and to accumulate reactive oxygen species (ROS) which is a potent inducer of NRF2." (PMID 29268703, 2017). "A combinatorial therapy targeting tumor hypoxia by using HIF-1α or VEGF-A inhibitors along with RT and immunotherapy (PD-L1 or other immune checkpoint inhibitor) may be beneficial for enhancing antitumor immunity in cancer patients." (PMID 28348554, 2017). "HIF1α also has been shown to impair membrane Hsp70 expression on tumor cells, and therefore might negatively affect NK cell recognition." (PMID 29093708, 2017). "Moreover, the administration of fascaplysin strongly reduced the accumulation of HIF-1α, which is a key transcriptional factor for regulating tumor angiogenesis in hypoxic tumor in vitro and in vivo." (PMID 28961193, 2017). "Tumor adaptation to hypoxia depends mostly on HIF-1α and HIF-2α." (PMID 29084538, 2017). "However, HIF-1α expression in CRC patients is correlated with tumor growth, angiogenesis, metastasis, and VEGF expression." (PMID 28177885, 2017). "The transcriptional program mastered by HIF1α stimulates invasiveness of tumor cells together with their angiogenic potential and further amplifies their metabolic rewiring, and succinate-dependent HIF1α induction turned out to be essential for the neoplastic growth of several tumor cells." (PMID 28405578, 2017).
tumor (continued). "Given aberrant tumor vessel is characterized by intense vascular leakage, we next investigated whether blockade of HIF-1α would reduce the vascular leakage, which was indicated by fitc-conjugated dextran leaking outside the vascular lumen." (PMID 29088755, 2017). "Finally, we found a marked reduction in genes modulated by HIF1α, a regulator of chemokine and adhesion molecules that facilitate interactions between tumor cells and the microenvironment." (PMID 29259203, 2017). "Therefore, the aim of this study was to investigate the effect of hypoxia on the expression of HIF-1α, RhoA, cdc42 and Rac1, RhoA activation, cell proliferation and migration using five tumor cell lines of different tissue origin." (PMID 28562340, 2017). "In summary, we demonstrated that Girdin could regulate the glycolysis of HCC cells via the PI3K/AKT/HIF-1α signaling pathway, which affects the sensitivity of tumor cells to radiotherapy." (PMID 28810896, 2017). "The inhibition of HIF-1α may alter the preferential metabolic pathway in cancer cells from glycolysis to oxidative phosphorylation to inhibit tumor metastasis." (PMID 28790395, 2017). "However, the tumor microenvironment in solid tumors is hypoxic, and c-Kit has been reported to participate in the formation of the tumor vasculature via promoting HIF-1α-mediated VEGF expression." (PMID 28573141, 2017). "Moreover, the role of NRF2 cross-talk with HIF-1α in tumor angiogenesis was shown by previous studies." (PMID 29268703, 2017). "Our results showed that pretreatment with candesartan, an AT1R blocker, reversed the resistance of hypoxic tumor cells to radiation exposure; this effect may correlate with the decreased HIF-1α expression due to Ang II signal-blocking in hypoxic tumor cells." (PMID 28205588, 2017). "Similarly, NOX4 promotes tumor angiogenesis through stabilization of HIF-1α and induction of VEGF expression." (PMID 28594389, 2017). "E.g. it could be shown that HIF-1α is able to promote tumor progression and to induce epithelial-mesenchymal transition (EMT) of tumor cells to facilitate metastasis." (PMID 29163780, 2017). "Given the important role of Ang II in HIF-1α accumulation in hypoxic tumor cells, we next assessed whether the enhanced Ang II levels contribute to radiation resistance of hypoxic tumor cells." (PMID 28205588, 2017). "A hypoxic environment may induce HIF-1α in the SGC tumour, and HIF-1α-induced ANGPTL4 may promote tumour growth by upregulation of c-Myc and downregulation of p27." (PMID 28894280, 2017). "Effects on tumor metabolism could be linked to inhibition of AKT and HIF-1α phosphorylation/expression by RICTOR blockade that we observed; since both factors are key players in metabolic reprogramming." (PMID 28445935, 2017). "Our findings demonstrated that Girdin could regulate the glycolysis of HCC cells through the PI3K/AKT/HIF-1α signaling pathway, which affects the sensitivity of tumor cells to radiotherapy." (PMID 28810896, 2017). "Thus, we measured the level of hypoxia-inducible factor (HIF)-1A, a specific marker of hypoxia, in tumor tissues by IHC." (PMID 27283989, 2017). "It has been shown that tumor cells recruit bone marrow-derived vascular endothelial progenitor cells (BM-EPCs) by increasing the expression of hypoxia-inducible factor-1α (HIF-1α) and vascular endothelial growth factor (VEGF), both of which play an important role in angiogenesis." (PMID 28573141, 2017). "Our findings revealed that high tumor tissue ascorbate level could limit the expression of HIF-1α and its targets in thyroid lesions." (PMID 29084538, 2017). "However, most studies have shown that elevated Hif-1a expression in tumor cells confers resistance to hypoxic exposure that ultimately contributes to tumor resistance to radiotherapy and chemotherapy." (PMID 29069822, 2017).
tumor (continued). "Additionally supporting the use of spheroids cultured under hypoxia as model system for hypoxic tumor regions, HIF-1-α shows strong accumulation in tumor spheroids cultured under hypoxia while it is only faintly detected in normoxic conditions." (PMID 28358364, 2017). "The most valuable finding is that compared with various biomarkers or volumetric methods, tumor hypoxia remained a major cause of treatment failure in patients with p16-negative PCs because GLUT1, VEGF, and HIF-1α were found to be associated with inferior outcomes." (PMID 29069791, 2017). "We show that either long-term exposure of cells to hypoxia (72 h) or increased expression of CHCHD4 in tumor cells leads to (i) the redistribution of the mitochondria to the perinuclear region of the cell, (ii) HIF-1α stabilization, and (iii) the upregulation of HIF targets." (PMID 28497026, 2017). "VEGF/HIF-1α/mammalian target of rapamycin (mTOR) signaling pathway could be related to the change of tumor metabolism; thus expression of mTOR might be altered by Bev therapy." (PMID 29262608, 2017). "As HIF-1α regulates transcription of its target genes, which are involved in angiogenesis, glucose metabolism, and metastasis in tumor progression, we determined the effects of Compound 12 on HIF-1 target gene expression at the mRNA level by semiquantitative RT-PCR." (PMID 27999195, 2017). "Given the importance of miR-1 in aerobic glycolysis in cancer cells, the results prompted us to examine whether activity of the miR-1/Smad3/ HIF-1α axis influenced tumor growth in vivo." (PMID 28471448, 2017). "HIF-1α activation could result in a ‘Warburg-like effect’ in HPV-related tumors under normoxia influencing tumor growth and improving cell survival." (PMID 29163780, 2017). "Moreover, β-catenin and HIF-1α interaction has been shown to regulate adaptation of tumor cells to hypoxia and drive HIF-mediated transcription." (PMID 28831110, 2017). "Inhibition of the hypoxic mediator, HIF-1α, and the activation factor in V-E cells, IL-8, which is closely related to tumor development, can potentially be used to develop a treatment that can directly regulate tumor development as well as the microenvironment of tumors." (PMID 28053598, 2017). "Recently, we demonstrated that one of the mechanisms by which Spry2 exerts its “tumor suppressor” functions is by decreasing the stability of HIF1α and HIF2α with a corresponding decrease in their ability to alter transcription of the HIF1α and HIF2α target genes." (PMID 28196140, 2017). "In addition, EMT-TFs also can regulate angiogenic factors and hypoxia-inducible factor-1 alpha (HIF-1α) to promote tumor angiogenesis in HCC." (PMID 28938653, 2017). "It appears that HIF-1α mediates catecholamine-induced tumor malignancy in some types of cancer." (PMID 28977888, 2017). "In RCC, overexpression of HIF-2α increases tumor growth, whereas HIF-1α shows a reverse effect." (PMID 28476028, 2017). "Furthermore, 4EBP1 and p70S6K1, which are regulated by growth factor-mediated mTOR signaling, control tumor development and progression through eIF4E-mediated cap-dependent translation of tumor promoting genes, such as survivin, HIF-1α, cyclin D1, and c-Myc." (PMID 28961193, 2017). "Therefore, it is of important to reveal what kind of tumor niche contributes to enhancement of the SIM2l-HIF-1α axis in CvSCC." (PMID 29109451, 2017). "Again, tumours that expressed VEGF grew significantly smaller in HIF-1α KO mice showed lower levels of sVEGFR1 and enhanced VEGFR2 signalling, resulting in non-productive angiogenesis, characterised by pericyte loss, increased hypoxia and tumour cell death." (PMID 29150606, 2017). "Moreover, we found significant correlation between MTA1 and HIF‐1α mRNA expression (r = 0.67; P = 0.034) in our own 10 prostatectomy tumor samples obtained immediately after surgery." (PMID 29024573, 2017). "HIF1-α is known to promote glycogen accumulation in both tumor and non-tumor cells." (PMID 28521819, 2017).
tumor (continued). "si-hVDAC also markedly decreased HIF1-α levels and tumor growth in U-87MG and U-118MG cancer cells." (PMID 28824871, 2017). "On the basis of literature data and our present results, GPER may be included among the transduction mediators involved in neovascularization triggered by HIF-1α/VEGF signaling axis in tumor microenvironment." (PMID 29212519, 2017). "Using the established SIRT3 knockdown or SIRT3 overexpressing gastric epithelial cells to investigate the role of SIRT3, we confirmed results from previous studies that suggested that SIRT3 functions as a tumor suppressor due to the suppression of ROS-mediated HIF-1α activation." (PMID 29108235, 2017). "Here, we show that HIF-1α is essential for controlling effector cell differentiation, migration, and function, as well as the expression of numerous costimulatory and exhaustion-related receptors in the tumor microenvironment." (PMID 29136509, 2017). "Re-establishing of HIF-1α degradation by interfering with the HPV-HIF-1α interaction might suppress tumor growth and metastasis." (PMID 29163780, 2017). "HIF-1α has recently been shown being participated in tumor glycometabolism." (PMID 29137372, 2017). "HIF-1α can either be upregulated due to oncogenic signaling or as a response to tumor hypoxia." (PMID 28404916, 2017). "Hence, DNA damage decreased under hypoxic stress and hypoxia-inducible factor 1α (HIF1α) is stabilized which in turn leads to promotion of tumor cell survival." (PMID 29093708, 2017). "demonstrate the importance of the HIF-1α/VEGF-A axis in tumor immunity." (PMID 29136509, 2017). "However, upon challenge with the tumour target cells YAC-1 and V-abl21, loss of HIF-1α reduced the fraction of CD107A-positive and IFN-γ-positive NK cells in normoxia and hypoxia." (PMID 29150606, 2017). "al. investigated HIF-1α expression in tumor tissue from 100 patients with sporadic MTC." (PMID 28404916, 2017). "Altogether, we suggest the possibility that a HIF-1α/LOX regulatory mechanism may act in synergy to foster tumor formation along with the adaptation of tumor cells to hypoxia." (PMID 28143503, 2017). "We reasoned that the immature tumour blood vessel phenotype in HIF-1α KO mice may enhance tumour cell intravasation and metastatic spread." (PMID 29150606, 2017). "In addition, treatment of Rag2M mice bearing MCF-7 tumor xenografts significantly decreased tumor hypoxia and increased mTORC1 activity as demonstrated by Western blot by reduced HIF-1α expression and increased S6K1 phosphorylation (Thr 412), respectively." (PMID 28280521, 2017). "Here, exercise reduced Hif1-α levels and slowed tumor cell proliferation and tumor growth." (PMID 29254140, 2017). "Consistently, tumours from HIF-1α KO mice showed an increase in extravasated albumin." (PMID 29150606, 2017). "Indeed, overexpression of HIF-1α/VEGF signaling is associated with increased vascular density, higher tumor grade, therapeutic resistance and poor prognosis." (PMID 29240722, 2017). "Furthermore, the tumor sizes of the injected NPC cells with HIF1α or PDRG1 overexpression were significantly larger than those of the control cells, as shown in the xenograft mice model." (PMID 28057028, 2017). "Our results showed that BA/CDM combination additively suppresses in vivo tumor growth in THP1 cells, and overexpression of SOD2/HIF1C diminishes this inhibition effect, indicating that BA/CDM exert additive inhibition effect on tumor growth through ROS generation and HIF1α pathway suppression." (PMID 29212263, 2017). "Loss of HIF-1α in NK cells resulted in a marked decrease of pericyte coverage, whereas overall tumour vessel density did not change." (PMID 29150606, 2017).
tumor (continued). "The hypoxia-inducible factor-1α (HIF-1α) plays a critical role in tumor angiogenesis." (PMID 28710377, 2017). "First, we disclose a novel mechanism by which hypoxia/HIF-1α shapes the tumor microenvironment." (PMID 28894087, 2017). "Furthermore, Rac1 also promotes tumor angiogenesis by inducing new vessel formation, and up-regulates the expression of HIF-1α and NF-κB, two major redox-dependent transcription factors induced by hypoxia environment." (PMID 28160553, 2017). "HIF-1α was a critical regulator in both tumor angiogenesis and hypoxia-induced EMT." (PMID 26856989, 2016). "In the process of VM formation by tumor cells, HIF-1α and EMT play an important role." (PMID 27806701, 2016). "We reason that one possible explanation for the diverse metabolic profiles may relate to the differential expression of Hypoxia Induced Factor-1a (HIF1α) in the tumor tissues." (PMID 27363021, 2016). "Thus, the pathways of HIF1α and of Myc are interlinked, and both genes regulate tumor promotion and progression." (PMID 26743088, 2016). "We presumed that ZnPP may reduce HIF-1α expression through inhibiting HO-1 activity, and consequently inhibit tumor proliferation." (PMID 26822586, 2016). "In hypoxia environment, HIF-1α can activate the adaptive response of the tumor target genes." (PMID 26853843, 2016). "Expression of HIF-1α was explored both in the epithelial and the stromal tumor component." (PMID 27634881, 2016). "Remarkably, hypoxic accumulation of HIF-1α was further amplified in NQO1 expressing cancer cells that may accelerate the tumour growth." (PMID 27966538, 2016). "RQI results were compared to patients’ age and sex, tumor site, kind of surgery, anastomosis failure, adenocarcinoma type and grade, tumor cell percentage, necrosis extent, HIF-1α and cleaved caspase-3 immunohistochemistry, and BRAF, KRAS and microsatellites status." (PMID 27124490, 2016). "Inhibition of HIF-1α expression by shRNA significantly reduced tumor growth in mice." (PMID 27191981, 2016). "HIF-1α was high also in the tumor tissue, which appeared to be reduced by ethanol feeding." (PMID 26951793, 2016). "Furthermore, the upregulation of Nrf2 is also related to angiogenesis which is promoted by HIF-1α, a transcription factor that senses oxygen homeostasis and is deregulated in tumours in hypoxic environments." (PMID 26697129, 2016). "Therefore, it is assumed that HIF-1α is facilitating carcinogenesis and tumor dissemination by promoting proliferation, angiogenesis, dedifferentiation and invasion." (PMID 27780920, 2016). "Thus, HIF-1α is a potential target for inhibition of both tumor-mediated angiogenesis and other aspects of tumor development, such as metabolic alterations that further increase the proliferation of tumor cells." (PMID 26882567, 2016). "HIF-1a upregulates production of target genes including VEGF in the tumor microenvironment." (PMID 27501793, 2016). "Indeed HIF-1α inhibitor has been confirmed a positive effect for depressing tumor growth and metastasis." (PMID 27708244, 2016). "As previously documented, HIF-1α is a crucial factor of hypoxia-induced tumor angiogenesis." (PMID 26933917, 2016). "In addition, MCU deletion impairs tumor growth and metastasis formation and inhibits ROS production and HIF‐1α expression, two major triggers of cancer progression." (PMID 27138568, 2016). "Chemokines are secreted small peptides that can induce migration of leukocytes, and subject to the direct regulation by hypoxia inducible factor 1α (HIF1α) and have been suggested to play an important role in tumor angiogenesis and metastasis in various cancers." (PMID 27716621, 2016). "Moreover, when these cells were implanted in nude mice we detected enhanced VEGF and HIF-1α expression, accompanied by significantly enhanced tumor growth and vessel density compared to mPGES-1−/− cells." (PMID 27322147, 2016).